SLC16A13 (solute carrier family 16 member 13)
Description:
Proton-linked monocarboxylate transporter. May catalyze the transport of monocarboxylates across the plasma membrane.
Synonyms: MCT13
Tractability: Antibody: UniProt places it where antibodies can reach, with medium confidence; UniProt predicts a signal peptide or a membrane-spanning region; its Gene Ontology location is reachable by antibodies, with medium confidence. PROTAC: ubiquitination databases record sites on it.
Gene: Protein-coding gene on chromosome 17 (7,036,015 to 7,040,117, forward strand). Ensembl gene ENSG00000174327.
Subcellular location: Golgi apparatus membrane; Cell membrane
Subcellular location (Human Protein Atlas): Golgi apparatus; Cytosol
Gene Ontology:
Molecular function: protein binding; monocarboxylic acid transmembrane transporter activity; transmembrane transporter activity
Biological process: monocarboxylic acid transport; transmembrane transport
Cellular component: Golgi apparatus; plasma membrane; Golgi membrane
Genetic constraint (gnomAD): Loss-of-function variants: 29 observed, 30.44 expected, observed/expected ratio (o/e) 0.95, 90% interval 0.71 to 1.3. The upper end of that interval is the gene's LOEUF score, 1.3, which puts it in group 5 of 6, group 1 being the genes least tolerant of losing a copy. Missense variants: 482 observed, 561.1 expected, observed/expected ratio (o/e) 0.86, 90% interval 0.8 to 0.93. Synonymous variants: 228 observed, 253.31 expected, observed/expected ratio (o/e) 0.9, 90% interval 0.81 to 1.
Homologues: Orthologues: chimpanzee SLC16A13 (99% identical), macaque SLC16A13 (97% identical), pig SLC16A13 (90% identical), guinea pig SLC16A13 (89% identical), mouse Slc16a13 (87% identical), dog SLC16A13 (87% identical), rabbit SLC16A13 (87% identical), zebrafish slc16a13 (51% identical), tropical clawed frog slc16a13 (50% identical), Drosophila melanogaster Sln (32% identical), Drosophila melanogaster Mct1 (30% identical), Caenorhabditis elegans mct-6 (30% identical), and 10 more. Paralogues in human: SLC16A11 (46% identical), SLC16A8 (35% identical), SLC16A7 (32% identical), SLC16A6 (31% identical), SLC16A12 (31% identical), SLC16A1 (31% identical), SLC16A3 (29% identical), SLC16A5 (28% identical), SLC16A9 (28% identical), SLC16A4 (27% identical), SLC16A14 (26% identical), SLC16A10 (23% identical), and 1 more.
Diseases named in the same sentence as SLC16A13 in open-access papers:
SLC16A13 is named in the same sentence as 16 diseases in open-access papers, as found by Europe PMC text mining. Sharing a sentence is not in itself a finding about the gene and the disease. The quoted sentences say what the papers report.
type 2 diabetes (7 papers, 2020 to 2025). "Genome-wide association studies have identified SLC16A13 as a novel susceptibility gene for type 2 diabetes." (PMID 34211098, 2021). "Slc16a13 is implicated in genome-wide association studies of type 2 diabetes, but it is unclear what function this gene might play in pigmentation or eye development." (PMID 32433666, 2020). "SLC16A13, which encodes the monocarboxylate transporter 13 (MCT13), is a susceptibility gene for type 2 diabetes and is expressed in the liver and duodenum." (PMID 37630718, 2023). "SLC16A13 encodes MCT13, which is a susceptibility gene for type 2 diabetes in Japanese and Chinese populations." (PMID 37630718, 2023). "A GWAS on genetic risk factors associated with type-2 diabetes across individuals from Mexico and Latin America identified a novel introgressed locus spanning SLC16A11 and SLC16A13 associated with type 2 diabetes." (PMID 36503519, 2022). "Existing studies have confirmed that MCT11(SLC16A11) and MCT13(SLC16A13) are related to type 2 diabetes, and MCT12(SLC16A12) is involved in the development of juvenile cataracts." (PMID 34424811, 2021). "This study suggests SLC16A13 as a potential target for the treatment of type 2 diabetes and non-alcoholic fatty liver disease." (PMID 34211098, 2021). "SLC16A13 is a lactate transporter expressed at the plasma membrane and a potential target for the treatment of type 2 diabetes and non-alcoholic fatty liver disease, while its role in tumor needs to be further explored." (PMID 34977043, 2021). "Together, these data suggest that SLC16A13 is a potential target for the treatment of type 2 diabetes and non-alcoholic fatty liver disease." (PMID 34211098, 2021). "Slc16a13 is not known to be important in pigmentation, and the function of this gene is poorly understood aside from recent GWAS studies implicating its potential involvement in type 2 diabetes." (PMID 32433666, 2020).
diabetes (5 papers, 2021 to 2024). "As a member of the same family, the SLC16A13 gene encoding MCT13 has also recently been identified as a potential susceptibility gene for diabetes." (PMID 39850557, 2024). "A variant of SLC16A13 gene was reported to be related to the development of diabetes mellitus in the Chinese population." (PMID 37630718, 2023). "In this research, we make explorations of the association between the rs312457 genotype of the SLC16a13 gene and diabetes in the Chinese population." (PMID 34257700, 2021). "In our study, the rs312457 genetic variation in SLC16a13 increased the risk of diabetes." (PMID 34257700, 2021). "The rs312457 genotype of the SLC16A13 gene was associated with the occurrence of diabetes in a Chinese population.The knockdown of Slc16a13 ameliorated hepatic lipid accumulation and insulin resistance in mice, indicating that SLC16A13 may be a potential therapeutic target for both T2D and NAFLD." (PMID 39850557, 2024). "SLC16A13 is a candidate gene for diabetes in mice, and its deletion will attenuate lipid accumulation and insulin resistance." (PMID 39834545, 2024). "We need to put further efforts into identifying the mechanism of SLC16a13 in the pathogenesis of diabetes mellitus and facilitate strategies of early diagnosis and preventative aiming at reducing this increased disease burden." (PMID 34257700, 2021). "Our results revealed that the rs312457 genotype of the SLC16a13 gene was correlated with the development of diabetes mellitus in the Chinese population." (PMID 34257700, 2021). "Despite its potential importance to diabetes development, the physiological function of SLC16A13 is unknown." (PMID 34211098, 2021). "However, the role of the rs312457 locus of the SLC16a13 gene in the pathogenesis of diabetes has not been reported yet." (PMID 34257700, 2021).
Insulin resistance (3 papers, 2021 to 2024). Increased resistance towards insulin, that is, diminished effectiveness of insulin in reducing blood glucose levels. "Here, we describe a causal relationship between SLC16A13 function and the development of insulin resistance and fatty liver, reflecting the phenotype associated with the SLC16A13 polymorphism in a cohort of Japanese people." (PMID 34211098, 2021). "Slc16a13 deficiency thereby attenuates hepatic diacylglycerol-PKCε mediated insulin resistance in obese mice." (PMID 34211098, 2021). "Finally, our study demonstrates that targeting SLC16A13 represents a promising therapeutic strategy for the treatment of fatty liver and insulin resistance at the same time." (PMID 34211098, 2021). "These human data provide evidence for an association between SLC16A13 gene expression and the development of adiposity, fatty liver, and insulin resistance independent of the described human polymorphism." (PMID 34211098, 2021). "To further investigate the potential role of the transporter in human metabolic disease, we analyzed SLC16A13 gene expression in human liver samples with different stages of NAFLD and insulin resistance." (PMID 34211098, 2021). "Together, our data suggest that Slc16a13 deletion attenuates the ectopic deposition of lipids in the liver, leading to a decrease in hepatic DAG content, lower PKCε activation, and, in turn, reduces diet-induced hepatic insulin resistance." (PMID 34211098, 2021).
pancreatic cancer (2 papers, 2020 to 2023). "It was reported that SLC16A13 could be a potential biomarker for tumor prognosis, including oral squamous cell carcinoma, lung adenocarcinoma, and pancreatic cancer." (PMID 38159261, 2023). "However, SLC16A11 and SLC16A13 are acting as favor prognosis genes for pancreatic cancer if higher than median expression in TCGA cohort." (PMID 32355273, 2020). "SLC16A1, SLC16A3 and SLC16A13 exhibited biomarker potential for prognosis, and we further identified their related genes and regulatory networks, revealing core molecular pathways that require further investigation for pancreatic cancer." (PMID 32355273, 2020). "The boxplot of the RNA-Seq expression in 179 pancreatic cancer vs 171 normal pancreas samples demonstrated that SLC16A1, SLC16A2, SLC16A3, SLC16A4, SLC16A5 and SLC16A13 were increased with statistical meaning." (PMID 32355273, 2020).
fatty liver (1 paper, 2021). "Hepatic SLC16A13 gene expression significantly correlated with waist circumference, BMI, HOMA-IR, and histologically assessed liver steatosis as well as with quantitatively measured liver TAG content." (PMID 34211098, 2021).
liver disease (1 paper, 2021). "Compared to MCT1, we speculate that SLC16A13 function is more relevant in liver disease and it may be the transporter mediating hepatic l-lactate influx during specific pathophysiological states." (PMID 34211098, 2021).
Obesity (1 paper, 2021). Accumulation of substantial excess body fat. "Loss of SLC16A13 function might counteract one of these mechanisms in the context of diet-induced obesity." (PMID 34211098, 2021). "Therefore, we studied SLC16A13 expression in human and mouse tissue and generated gain- and loss-of-function models, including Slc16a13 knockout mice that were metabolically characterized in the context of diet-induced obesity." (PMID 34211098, 2021). "To address this point, we analyzed Slc16a13 gene expression under conditions of obesity." (PMID 34211098, 2021). "Diet-induced obesity may lead to dysregulation of Slc16a13 expression, making it impossible to regulate it normally during fasting." (PMID 34211098, 2021). "Both human and mouse expression data do not indicate whether SLC16A13 deregulation is causal or just a consequence of metabolic alterations in the context of obesity." (PMID 34211098, 2021). "In the context of diet-induced obesity, the knockout of Slc16a13 did not significantly affect body weight, body composition, or energy expenditure, suggesting obesity might mask the Slc16a13-dependent effect on body composition seen in NCD-fed mice." (PMID 34211098, 2021).
viral infection (1 paper, 2025). "Notably, WNT5A, SELENON, and SLC16A13 exerted similar enhancing effects on both the single-stranded negative-sense RNA virus BPIV-3c and the single-stranded positive-sense RNA virus BEV, highlighting their broad and critical roles in facilitating viral infection." (PMID 41328592, 2025).
cancer (1 paper, 2021). A tumor composed of atypical neoplastic, often pleomorphic cells that invade other tissues. "However, studies on SLC16A4, SLC16A10, SLC16A11, SLC16A13, and SLC16A14 in cancer are still lacking." (PMID 34424811, 2021).
infection (1 paper, 2025). The state of being infected such as from the introduction of a foreign agent such as serum, vaccine, antigenic substance or organism. "We further confirmed that WNT5A, SELENON, and SLC16A13 are key host factors involved in infection by BPIV-3a, as well as by BPIV-3c and other bovine RNA viruses (e.g. BEV)." (PMID 41328592, 2025). "We then investigated SLC16A13’s impact on the BPIV-3a replication cycle: measuring viral titers at multiple time points post-infection (MOI 0.1) showed that SLC16A13 KO affected the late stage of BPIV-3a replication." (PMID 41328592, 2025).
metabolic disease (1 paper, 2021). A congenital disorder (due to inherited enzyme abnormality) or acquired (due to failure of a metabolically important organ) disorder resulting from an abnormal metabolic process. "Therefore, it seems reasonable to also investigate SLC16A13 in the context of T2D susceptibility; besides, the function and role of SLC16A13 in metabolic disease are completely unknown." (PMID 34211098, 2021). "There are several advantages of SLC16A13/MCT13 over MCT1 in terms of a pharmacological target for the treatment of metabolic disease: First, homozygous deletion in mice leads to viable offspring, which is not the case in Slc16a1 knockout mice." (PMID 34211098, 2021). "Because the human SLC16A13 polymorphism is associated with T2D, we speculated that SLC16A13 expression and/or protein function might also be dysregulated in the context of metabolic disease independent of the known polymorphism." (PMID 34211098, 2021). "Therefore, SLC16A13 may be a lactate transporter that is quickly saturated, but whose high affinity enables to react to minor changes in plasma lactate concentrations in the early stages of metabolic disease." (PMID 34211098, 2021). "Contrary to mice, human SLC16A13 shows its highest expression in the liver, and kidney SLC16A13 may not be crucial in human metabolic disease." (PMID 34211098, 2021).
SLC16A13 also shares sentences with these, for which no sentence is quoted: non-alcoholic fatty liver disease (2 papers); tumor (2); liver (1); lung adenocarcinoma (1); oral squamous cell carcinoma (1).